MYLK (myosin light chain kinase)
Description:
Calcium/calmodulin-dependent myosin light chain kinase implicated in smooth muscle contraction via phosphorylation of myosin light chains (MLC). Also regulates actin-myosin interaction through a non-kinase activity. Phosphorylates PTK2B/PYK2 and myosin light-chains. Involved in the inflammatory response (e.g. apoptosis, vascular permeability, leukocyte diapedesis), cell motility and morphology, airway hyperreactivity and other activities relevant to asthma. Required for tonic airway smooth muscle contraction that is necessary for physiological and asthmatic airway resistance. Necessary for gastrointestinal motility. Implicated in the regulation of endothelial as well as vascular permeability, probably via the regulation of cytoskeletal rearrangements. In the nervous system it has been shown to control the growth initiation of astrocytic processes in culture and to participate in transmitter release at synapses formed between cultured sympathetic ganglion cells. Critical participant in signaling sequences that result in fibroblast apoptosis. Plays a role in the regulation of epithelial cell survival. Required for epithelial wound healing, especially during actomyosin ring contraction during purse-string wound closure. Mediates RhoA-dependent membrane blebbing. Triggers TRPC5 channel activity in a calcium-dependent signaling, by inducing its subcellular localization at the plasma membrane. Promotes cell migration (including tumor cells) and tumor metastasis. PTK2B/PYK2 activation by phosphorylation mediates ITGB2 activation and is thus essential to trigger neutrophil transmigration during acute lung injury (ALI). May regulate optic nerve head astrocyte migration. Probably involved in mitotic cytoskeletal regulation. Regulates tight junction probably by modulating ZO-1 exchange in the perijunctional actomyosin ring. Mediates burn-induced microvascular barrier injury; triggers endothelial contraction in the development of microvascular hyperpermeability by phosphorylating MLC. Essential for intestinal barrier dysfunction. Mediates Giardia spp.-mediated reduced epithelial barrier function during giardiasis intestinal infection via reorganization of cytoskeletal F-actin and tight junctional ZO-1. Necessary for hypotonicity-induced Ca(2+) entry and subsequent activation of volume-sensitive organic osmolyte/anion channels (VSOAC) in cervical cancer cells. Responsible for high proliferative ability of breast cancer cells through anti-apoptosis.
Synonyms: MLCK; smMLCK; KRP; MLCK1; MYLK1; Telokin; MLCK108; MLCK210; MYLK-L; AAT7; MMIHS; MMIHS1; MSTP083
Tractability: Small molecule: a high-quality ligand is known; it belongs to a druggable protein family. Antibody: its Gene Ontology location is reachable by antibodies, with high confidence. PROTAC: its protein half-life has been measured; a small molecule that binds it is known.
Target class: Kinase; CAMK protein kinase MLCK family; CAMK protein kinase group; Enzyme; Protein Kinase
Gene: Protein-coding gene on chromosome 3 (123,610,049 to 123,884,375, reverse strand). Ensembl gene ENSG00000065534.
Subcellular location: Cytoplasm; Cell projection, lamellipodium; Cleavage furrow; Cytoplasm, cytoskeleton, stress fiber
Subcellular location (Human Protein Atlas): Actin filaments; Plasma membrane
Pathways (Reactome):
Muscle contraction: Smooth Muscle Contraction
Signal Transduction: RHO GTPases activate PAKs
Gene Ontology:
Molecular function: myosin light chain kinase activity; protein binding; scaffold protein binding; ATP binding; protein kinase activity
Biological process: aorta smooth muscle tissue morphogenesis; bleb assembly; cellular hypotonic response; positive regulation of calcium ion transport; positive regulation of cell migration; positive regulation of wound healing; positive regulation of vascular associated smooth muscle contraction; protein phosphorylation; smooth muscle contraction; tonic smooth muscle contraction; muscle organ development; regulation of synaptic vesicle endocytosis
Cellular component: actin cytoskeleton; cleavage furrow; cytoplasm; lamellipodium; plasma membrane; stress fiber; cytosol; synapse
Genetic constraint (gnomAD): Loss-of-function variants: 105 observed, 204.49 expected, observed/expected ratio (o/e) 0.51, 90% interval 0.44 to 0.6. The upper end of that interval is the gene's LOEUF score, 0.6, which puts it in group 2 of 6, group 1 being the genes least tolerant of losing a copy. Missense variants: 2,067 observed, 2,500.7 expected, observed/expected ratio (o/e) 0.83, 90% interval 0.8 to 0.86. Synonymous variants: 866 observed, 977.69 expected, observed/expected ratio (o/e) 0.89, 90% interval 0.84 to 0.94.
Gene-disease validity (ClinGen):
ClinGen rates the evidence that MYLK causes each of these diseases.
familial thoracic aortic aneurysm and aortic dissection (autosomal dominant): Strong. A rare genetic vascular disease characterized by the familial occurrence of thoracic aortic aneurysm, dissection or dilatation affecting one or more aortic segments (aortic root, ascending aorta, arch or descending aorta) in the absence of any other associated disease.
Homologues: Orthologues: chimpanzee MYLK (99% identical), macaque MYLK (97% identical), dog MYLK (89% identical), pig MYLK (87% identical), guinea pig MYLK (86% identical), rat Mylk (86% identical), mouse Mylk (85% identical), zebrafish mylka (31% identical), zebrafish mylkb (31% identical). Paralogues in human: DAPK1 (9% identical), DAPK3 (8% identical), DAPK2 (7% identical), NEXN (6% identical).
Diseases named in the same sentence as MYLK in open-access papers:
MYLK is named in the same sentence as 164 diseases in open-access papers, as found by Europe PMC text mining. Sharing a sentence is not in itself a finding about the gene and the disease. The quoted sentences say what the papers report.
breast cancer (29 papers, 2012 to 2024). A primary or metastatic malignant neoplasm involving the breast. "In breast cancer, a reduction in MYLK activity has been linked to activation of the extracellular signal-regulated kinase (ERK1/2) pathway." (PMID 39129004, 2024). "MYLK expression was downregulated in breast cancer, and loss of MYLK led to the disruption of cell–cell adhesion and invasive behavior of breast epithelial cells." (PMID 39596804, 2024). "Expression of MYLK is downregulated in breast cancer and loss of MYLK leads to disruption of cell–cell adhesion and invasive behavior of breast epithelial cells." (PMID 33800915, 2021). "Previous studies have reported that MYLK regulates cell migration in several cancers, including melanoma, gastric, liver, lung, bladder, prostate and breast cancers." (PMID 35278271, 2022). "Myosin light-chain kinase is known to play a role in the proliferation and migration of breast cancer cells." (PMID 29156751, 2017). "We analyzed a publicly available mRNA and miRNA microarray dataset from 101 breast cancer patients and observed significant inverse correlations of miR-200c with its target genes MYLK, TKS5 and ZEB1." (PMID 26334100, 2015). "Analysis of gene expression 56 breast cancer cell lines from the Cancer Cell Line Encyclopedia (CCLE) panel also showed high positive correlations between MYLK/TKS5 and ZEB1." (PMID 26334100, 2015). "In summary, we here identified two direct miR-200c target genes, TKS5 and MYLK that are both necessary for invasion and invadopodia formation of breast cancer cells." (PMID 26334100, 2015). "Depletion of TKS5 or MYLK in breast cancer cells reduced their invasive potential and their ability to form invadopodia." (PMID 26334100, 2015). "Whereas TKS5 is already known to be involved in invadopodia formation, we further identified MYLK as a new player in invadopodia formation that is essential for the invasion of breast cancer cells." (PMID 26334100, 2015). "In this study, we used a breast cancer model to examine the effects of radiation alone or in combination with estrogens on the expression of genes linked to cell motility, such as ADAM12, CYR61, FLRT2, SLIT2, VNN1, MYLK, MAP1B, and TUBA1A." (PMID 39596804, 2024). "Though the exact relationship between MYLK and estrogen receptors remains to be elucidated, understanding this relationship could be essential to comprehend how the motile phenotype of breast cancer cells is influenced by estrogen receptor expression." (PMID 39596804, 2024). "Additionally, MYLK is a key participant in cell progression of breast cancer, prostate cancer and colon cancer." (PMID 34733825, 2021). "Importantly, few of these proteins, namely, ATP1B2, CTNNA3 and MYLK were reported to be downregulated biomarkers in glioma, hepatocellular and breast carcinoma, respectively." (PMID 34728699, 2021). "MYLK was important for pathogenesis of breast cancer through the inhibition of apoptosis, but this gene may be associated with the inhibition of apoptosis in GBM." (PMID 31137733, 2019). "Barkanet al. found that the engagement of ITGB1 and downstream signaling through the activation of FAK, Src, ERK1/2, and myosin light-chain kinase (MLCK) was responsible for the dormant-to-proliferative switch of D2.0R mammary tumor cells bothin vitro andin vivo." (PMID 29263786, 2017). "MYLK is associated with breast tumor metastasis through in vitro studies showing its role in mediating migration and invasion of the MDA-MB-231 cell-line and the intravasation of breast cancer cells through an endothelial cell layer." (PMID 24944582, 2014). "According to the findings, MYLK and estrogen receptor gene expression had a positive correlation with ESR1 in patients with Her2 and with ESR2 expression in patients with Luminal A breast cancer." (PMID 39596804, 2024).
breast cancer (continued). "According to a bioinformatic study, the expression of the genes FLRT2, SLIT2, VNN1, MAP1B, MYLK, and TUBA1A was found to be higher in normal tissue than in malignant tissue in patients with breast cancer." (PMID 39596804, 2024). "Conversely, in the mouse mammary tumour cell line 168FARN, the knockdown of ANXA1 inhibited the invasion and metastasis of breast cancer, with less expression of epithelial–mesenchymal transition (EMT) markers, wave proteins and myosin light-chain kinase." (PMID 36936694, 2023). "We then analyzed the expression levels of SIK2, phosphorylated MYL2 and phosphorylated MYLK in ovarian cancer cell lines (SKOV3, OVCAR8, OVCAR5, OVCAR3 and OVISE) and human breast cancer cell lines (MDA‐MB‐231 and Hs578 t)." (PMID 35278271, 2022). "In another study on breast cancer, novel validated targets of miR-200c, SH3 and PX domains 2A (TKS5), and myosin light chain kinase (MYLK) were downregulated by miR-200c through the ZEB1 pathway." (PMID 27601996, 2016). "Indicating clinical relevance, MYLK and TKS5 levels also correlate positively with ZEB1-, but negatively with E-cadherin and miR-200-levels in human breast cancer samples." (PMID 26334100, 2015). "We identified downregulated CARs in vicinity or overlapping the oncogenes IGF1R, MYLK, the breast cancer drug target OGT (O-GlcNAc transferase), and the breast cancer-related cyclin CCNL1." (PMID 25264628, 2014). "Moreover, RAC1, CDC42, MYL9, MYLK, ABL1, and other genes have been proved to be related to the progress of human breast cancer." (PMID 33306680, 2020). "In addition, integrating pathway and gene information, we identified five (ID4, ANXA4, CXCL9, MYLK, FBXL7) and six (SQLE, E2F1, PTTG1, TSTA3, BUB1B, MAD2L1) known cancer genes significant for ovarian and breast cancer respectively." (PMID 22759382, 2012). "In this work, we could further clarify the detailed functions of the ZEB1/miR-200 feedback loop in tumor invasion by identifying MYLK and TKS5 as two novel miR-200 target genes, that are both necessary for invadopodia formation and invasion of breast cancer cells." (PMID 26334100, 2015). "Bioinformatic analysis indicated that FLERT2, SLIT2, VNN1, MAP1B, MYLK, and TUBA1A gene expressions were found to be higher in normal tissue than in tumor tissue of breast cancer patients." (PMID 39596804, 2024).
bladder cancer (26 papers, 2017 to 2025). "MYLK over-expression is linked to poor survival in bladder carcinoma, colorectal carcinoma, and hepatocellular carcinoma." (PMID 34090518, 2021). "MYLK is highly expressed in bladder cancer and is associated with a poor clinical prognosis." (PMID 39762799, 2025). "More specifically, circ-MYLK is upregulated in bladder cancer cells and tissues and its expression is positively correlated to the progression of tumor stage and grade." (PMID 34205978, 2021). "For instance, circRNA MYLK promotes bladder cancer progression and metastasis via enhancing cancer cell growth and angiogenesis." (PMID 33372356, 2021). "An exemplary case of circRNA-mediated signaling crosstalk in cancer is the effect of circ-MYLK on bladder cancer progression." (PMID 34205978, 2021). "The circular RNA MYLK (circMYLK) has been reported to be involved in the development of malignant tumours, including liver, prostate and bladder cancers." (PMID 32342645, 2020). "A previous study suggested that circRNA MYLK (circMYLK) acts as a ceRNA to promote the proliferation and metastasis of bladder cancer by modulating the VEGFA/VEGFR2 signalling pathway." (PMID 32342645, 2020). "Collectively, these results supported the idea that the MAP1A/miR-34a-5p/LINC0667/circ_MYLK/circ_MAP1B ceRNA network may play a role in the pathological processes of bladder cancer." (PMID 36408130, 2022). "For example, circRNA ZNF609 functions as a competitive endogenous RNA to regulate FOXP4 expression by sponging miR-138-5p in renal carcinoma.CircRNA MYLK binds to miR-29a and promotes epithelial-mesenchymal transition and xenograft growth, angiogenesis, and metastasis of bladder cancer." (PMID 30736838, 2019). "Circular RNA MYLK regulates VEGFA/VEGFR2 signaling pathway and promotes cancer progression through serving as a ceRNA of miR-29a in bladder cancer." (PMID 32497020, 2020). "Second, significantly altered miRNAs in recurrent bladder cancer were identified, with miR-154-5p showing the highest level of editing in recurrent bladder cancer and may up-regulate the expression levels of downstream targets HS3ST3A1, AQP9, MYLK, and RAB23." (PMID 36199571, 2022). "Studies have shown that circMYLK produced by human myosin light chain kinase (MYLK) can competitively bind to miR-29a, abolishing miR-29a inhibition of VEGFA/VEGFR2 and downstream Ras/ERK signaling pathways, thereby promoting epithelial-mesenchymal transition and bladder cancer development." (PMID 34786637, 2022).
gastric cancer (16 papers, 2007 to 2024). A primary or metastatic malignant neoplasm involving the stomach. "Hypermethylation of MYLK serves as a circulating diagnostic marker of gastric carcinoma." (PMID 35178409, 2021). "Some kinases (e.g. PRKACA, CSNK2A1 and MAPK1) were found specifically dysregulated across multiple tumour types, but more than half were dysregulated in just one tissue (68%) such as MYLK kinase in stomach cancer and MTOR in kidney cancer." (PMID 36688815, 2023). "Regarding miR-181a-2-3p it has been shown in gastric carcinoma cell lines that this miRNA is highly upregulated and promotes tumor growth by targeting MYLK." (PMID 36158656, 2022). "It has also been reported that MYLK promotes progression and metastasis of hepatocellular carcinoma and gastric cancer." (PMID 31795319, 2019). "Myosin light chain kinase on chromosome 3, has a role in epithelial tight junction permeability, has been shown to be a warning marker for gastric cancer and has also been shown to promote cell proliferation." (PMID 28350786, 2017). "Changes of cells morphology and reduced CD24 and MYLK expression further supported the conclusion that depression of cell mobility could be the major consequence of MTA2 knockdown in gastric cancer cells." (PMID 25929737, 2015). "Among the 10 target genes, the expression of MYLK, RET and SLC6A8 was down regulated in gastric cancer, while the expression of the other 7 genes was up-regulated in gastric cancer." (PMID 34249673, 2021).
asthma (14 papers, 2008 to 2024). "For MYLK, common variants in intronic regions have been associated with inflammatory lung diseases, as well as the risk of asthma and coronary artery disease." (PMID 33531528, 2021). "MLCK has similar activity in asthmatic and in lung inflammation, and variation of the MYLK gene is strongly associated with acute lung injury and asthma susceptibility." (PMID 28588494, 2017). "Myosin light-chain kinase (MYLK) is a gene known to be significantly associated with severe asthma in African Americans." (PMID 25271083, 2015). "MYLK genetic variants confer increased risk of sepsis and sepsis-associated with acute lung injury and a more severe asthma phenotype in individuals of African ancestry." (PMID 18716680, 2008). "Myosin light chain kinase (MLCK) is implicated in the autoimmune reactions associated with asthma." (PMID 38474348, 2024). "Certain MYLK polymorphisms may be associated with severe respiratory inflammatory disorders, such as asthma, acute respiratory distress syndrome, etc.." (PMID 36834577, 2023). "We have previously demonstrated that MYLK SNPs confer increased susceptibility to inflammatory disease that drives disease severity and mortality, particularly in African descent subjects with asthma and acute inflammatory lung injury." (PMID 30161129, 2018). "Finally, nmMLCK expression of 721C- and 721T-containing MYLK transgenes were compared in nmMLCK−/− mice and confirmed deleterious effects of nmMLCK expression on asthmatic indices and implicated the augmented influence of MYLK 721C>T (c.439C>T) SNP on asthma severity." (PMID 25271083, 2015). "The confirmation of the novel mechanism of the regulation of asthmatic inflammation by a MYLK advances knowledge of the genetic basis for asthma disparities, and further suggests the potential of nmMLCK as a therapeutic target." (PMID 25271083, 2015). "Of these genes, CFB was induced in all patients, whereas BMP6 solely in allergic rhinitis patients and MYLK in allergic rhinitis patients with asthma." (PMID 24475887, 2014). "Furthermore, the chromosome location of MYLK (3q21) is an active site for several inflammatory disorders including asthma, allergic rhinitis, COPD and atopic dermatitis." (PMID 36362426, 2022). "Here we further examine the molecular function of a single-nucleotide polymorphism (SNP), located in the non-muscle myosin light-chain kinase isoform (nmMLCK), in asthma susceptibility and pathobiology." (PMID 25271083, 2015). "Three MYLK SNPs (P21H, S147P, V261A) alter the N-terminal amino acid sequence of the non-muscle isoform of MLCK (nmMLCK) and are highly associated with susceptibility to acute lung injury (ALI) and asthma, especially in individuals of African descent." (PMID 26111161, 2015). "Indeed, myosin light chain kinase (MLCK), which phosphorylates the myosin light chain, is increased in asthma at the mRNA level and a variant of the MLCK gene has been associated with severe asthma in African Americans." (PMID 23319963, 2012). "Several chemicals have been found to reduce ASM gel contraction in vitro including inhibitors of phospholipase C, myosin light chain kinase, Rho kinase, and NOX4 and thus this has identified these enzymes as potential targets for future novel asthma treatments." (PMID 23577039, 2013).